SSBP4 (single stranded DNA binding protein 4)
Tractability: Small molecule: a structure with a bound ligand is known. PROTAC: ubiquitination databases record sites on it.
Gene: Protein-coding gene on chromosome 19 (18,418,864 to 18,434,563, forward strand). Ensembl gene ENSG00000130511.
Subcellular location: Nucleus
Subcellular location (Human Protein Atlas): Nucleoplasm
Gene Ontology:
Molecular function: protein binding; transcription coactivator activity; single-stranded DNA binding
Biological process: positive regulation of transcription by RNA polymerase II
Cellular component: nucleus
Genetic constraint (gnomAD): Loss-of-function variants: 27 observed, 51.48 expected, observed/expected ratio (o/e) 0.52, 90% interval 0.39 to 0.72. The synonymous counts are far from expectation, so gnomAD's model fits this gene poorly and the ratio says little. Missense variants: 526 observed, 445.09 expected, observed/expected ratio (o/e) 1.18, 90% interval 1.1 to 1.27. Synonymous variants: 224 observed, 176.87 expected, observed/expected ratio (o/e) 1.27, 90% interval 1.13 to 1.41.
Homologues: Orthologues: macaque SSBP4 (97% identical), pig SSBP4 (92% identical), mouse Ssbp4 (84% identical), rat Ssbp4 (83% identical), dog SSBP4 (82% identical), zebrafish ssbp4 (80% identical), zebrafish SSBP4 (78% identical), tropical clawed frog ssbp4 (78% identical), guinea pig SSBP4 (58% identical), Drosophila melanogaster Ssdp (56% identical), Caenorhabditis elegans sam-10 (36% identical), Caenorhabditis elegans Y53F4B.5 (11% identical). Paralogues in human: SSBP3 (74% identical), SSBP2 (70% identical).
Diseases named in the same sentence as SSBP4 in open-access papers:
SSBP4 is named in the same sentence as 5 diseases in open-access papers, as found by Europe PMC text mining. Sharing a sentence is not in itself a finding about the gene and the disease. The quoted sentences say what the papers report.
breast carcinoma (1 paper, 2021). "In the analysis of the correlation between overall survival and significant DEG expression (CLDN7, MLLT10, RBM33, SH3RF1, SSBP4, and UBE2Z) in breast cancer, we found a shorter survival time based on GSE5881 and GSE42568 (P< 0.05)." (PMID 34151730, 2021). "Significantly overexpressed genes (CLDN7, MLLT10, RBM33, SH3RF1, SSBP4, and UBE2Z) were correlated with shorter survival, whereas underexpressed genes (BMPER, FGF7, MSRB3, and TNRC6B) were correlated with longer survival in breast cancer." (PMID 34151730, 2021).
psoriasis (1 paper, 2023). An autoimmune condition characterized by red, well-delineated plaques with silvery scales that are usually on the extensor surfaces and scalp. "In this study, we identified three novel genes associated with psoriasis after the conditional and joint analysis: LRRC25, SSBP4, and ELL." (PMID 37511476, 2023). "We also identified five novel psoriasis risk genes, methionine sulfoxide reductase A, elongation factor for RNA polymerase II (ELL), Myotubularin Related Protein 9 (MTMR9), leucine-rich repeat containing 25 (LRRC25), and single-stranded-DNA-binding protein 4 (SSBP4), among 26 genes." (PMID 37511476, 2023).
SSBP4 also shares sentences with these, for which no sentence is quoted: metastatic tumor (1 paper); pancreatic adenocarcinoma (1); tumor (1).